ARF4 (ARF GTPase 4)
Diseases named in the same sentence as ARF4 in open-access papers:
ARF4 is named in the same sentence as 36 diseases in open-access papers, as found by Europe PMC text mining. Sharing a sentence is not in itself a finding about the gene and the disease. The quoted sentences say what the papers report.
breast carcinoma (6 papers, 2018 to 2023). "In breast cancer patients, a surge in gene expression linked to ER-Golgi transport processes is evident, exemplified by genes like ARF4, COPB1, and USO1." (PMID 37762375, 2023). "ARF4 has also been associated with the regulation of breast cancer cell migration in response to Phorbol-12-Myristate 13-Acetate (PMA)." (PMID 32426352, 2020). "A comprehensive meta-analysis of breast cancer cells also unravels that the expression patterns of ARF4, COPB1, and USO1 are orchestrated by the CREB3-like transcription factors." (PMID 37762375, 2023). "Together with the upregulation of COPB1 and USO1, which encode for the COPI subunit β1 and General vesicular transport factor p115, respectively and regulate ER-Golgi trafficking, ARF4 has been reported to be upregulated in breast cancer patient samples." (PMID 32426352, 2020). "ARF4 serves as a positive regulator in breast cancer cell migration." (PMID 32151082, 2020). "Interestingly, ARF4 is described as an oncogene by promoting breast cancer cell migration and metastasis to the lungs." (PMID 32899424, 2020). "ARF4 has been reported to increases AP-1 promoter activity and induce breast cancer cell migration." (PMID 29862288, 2018). "The discoveries highlight the pivotal roles that ARF4, COPB1, and USO1 undertake in breast cancer cell proliferation and invasiveness." (PMID 37762375, 2023). "This establishes a role for ARF4, COPB1, and USO1 in the regulation of breast cancer cell growth and invasion through the retrograde transport of proteins from the Golgi to ER via COPI-coated vesicles." (PMID 32426352, 2020). "It is worth noting that in this study, 8 (ACTR3, ARF4, PGRMC1, RPS23, WDR12, ACTR2, SIAH1, and RPS27L) of 12 hub genes are related to cancers, such as lung cancer, epithelial ovarian cancer, gastric cancer, glioblastoma, breast cancer, and esophageal cancer." (PMID 33391181, 2020).
glioblastoma (6 papers, 2013 to 2024). The most malignant astrocytic tumor (WHO grade IV). "The ARF4 has also been proposed as an antiapoptotic gene in human glioblastoma-derived U373MG cells." (PMID 23634293, 2013). "Another gene in Merged module is ADP-ribosylation factor 4 (ARF4) that activates EGFR signaling has an anti-apoptotic function in human glioblastoma-derived U373MG cells." (PMID 23874428, 2013).
lung carcinoma (4 papers, 2020 to 2023). "ARF4 (a member of the RAS superfamily) is a small guanine nucleotide-binding protein and overexpression of ARF4 has been observed in human tumors, including ovarian cancer, lung cancer, and glioma." (PMID 32151082, 2020). "Upregulation of Arf1, Arf4, and Arf6 were found in breast, gastric, prostate, or lung cancer." (PMID 37182141, 2023).
retinal degeneration (4 papers, 2007 to 2025). Degeneration of the retina. "Therefore, Arf4 knockout was predicted to affect rhodopsin localization and likely photoreceptor health, as rhodopsin mislocalization is associated with retinal degeneration." (PMID 28410364, 2017). "Mutations that affect the rhodopsin sorting signal interfere with interactions between Arf4 and rhodopsin, leading to an aberrant trafficking and the initiation of retinal degeneration." (PMID 17327826, 2007). "Additionally, expression of Arf4 mutant deficient in ASAP1-mediated GTP hydrolysis disrupted rhodopsin trafficking and caused retinal degeneration." (PMID 39774853, 2025). "While our work clearly demonstrated the absence of Arf4 does not cause retinal degeneration or cystic kidney disease, Arf4 is a critical protein in post-natal mouse development." (PMID 28410364, 2017). "Since ciliary dysfunction causes retinal degeneration and cystic disease, our findings indicate that Arf4 does not play a role in ciliary function." (PMID 28410364, 2017). "Arf4 deletion in photoreceptors did not cause protein mislocalization or retinal degeneration, as expected if Arf4 played a role in protein transport to the ciliary outer segment." (PMID 28410364, 2017). "This suggests that Arf4 may be an important player in human diseases such as retinal degeneration and polycystic kidney disease." (PMID 24586199, 2014).
ciliopathy (3 papers, 2014 to 2023). A genetic disorder of the cellular cilia or the cilia anchoring structures, the basal bodies, or of ciliary function. "To better understand the function of Arf4 and its possible role in ciliopathies, we created an Arf4 mutant mouse." (PMID 24586199, 2014). "It is therefore plausible to hypothesize that Arf4 regulates radial migration by facilitating the ciliary transport of these ciliopathy-related gene products." (PMID 37848288, 2023). "To determine if Arf4 is a global regulator of ciliary protein trafficking we created an Arf4 genetrap mouse with the prediction that if it plays this role, the mouse should have ciliopathy phenotypes." (PMID 24586199, 2014).
ovarian carcinoma (3 papers, 2019 to 2020). A malignant neoplasm originating from the surface ovarian epithelium. "In contrast, miR-221 inhibits tumor progression in diseases such as pancreatic and ovarian cancers, by targeting factors, such as SOCS3 and ADP-ribosylation factor-4 (ARF4)." (PMID 31470827, 2019).
thyroid cancer (3 papers, 2020 to 2025). "The combined downregulation of ARF4 and upregulation of miR-222 might indicate its diagnostic specificity in thyroid cancer." (PMID 32899424, 2020). "Furthermore, examples of universal NIS trafficking mechanisms, e.g. ARF4 and VCP regulation, exist in both breast and thyroid cancer cells." (PMID 40748136, 2025).
diabetes (2 papers, 2022 to 2024). "We showed that 25‐HC was able to interrupt ASAP1‐ARF4 interaction, thereby increasing ARF4 activity and preventing cells from apoptosis in the context of diabetes." (PMID 38816950, 2024). "However, our data suggest that ARF4 has a significant renoprotective effect in the context of diabetes." (PMID 38816950, 2024). "Using genetic and pharmacological approaches, our study now demonstrates that 25‐HC, the enzymatic product of CH25H, provides renoprotection in diabetic kidneys by binding to and enhancing the activation of ADP ribosylation factor‐4 (ARF4)." (PMID 38816950, 2024). "ATF3, ADP ribosylation factor-4 (ARF4), cAMP response element binding protein-3 (CREB3), and Component Of Oligomeric Golgi Complex-6 (COG6) were identified as potential Golgi regulatory factors that are dysregulated in both major forms of diabetes." (PMID 35204835, 2022).
Alzheimer disease (1 paper, 2012). A progressive, neurodegenerative disease characterized by loss of function and death of nerve cells in several areas of the brain leading to loss of cognitive function such as memory and language. "In addition, Arf4 overexpression rescues spine loss in primary neurons from an Alzheimer's disease-related apolipoprotein (apo) E4 mouse model." (PMID 23050017, 2012).
Anxiety (1 paper, 2012). Intense feelings of nervousness, tension, or panic often arise in response to interpersonal stresses. "Arf4+/− mice were also not impaired in locomotor and exploratory activity (open field test), motor coordination (rotarod), or anxiety-related behaviors (elevated plus maze)." (PMID 23050017, 2012).
cervical cancer (1 paper, 2020). A primary or metastatic malignant neoplasm involving the cervix. "Our findings were consistent with these previous results, and showed that increased mRNA levels of ARF4 and BSG were abnormally overexpressed in cervical cancer samples and its expression correlated with poorer patient prognosis." (PMID 32151082, 2020).
Chlamydia infection (1 paper, 2017). "Altogether, these data suggest that CT813 uses ARF1 and ARF4 to control Golgi complex positioning during Chlamydia infection." (PMID 28465429, 2017). "Our observation that CT813, ARF1, and ARF4 are key players in Golgi complex positioning thus raised the possibility that they are involved in the manipulation of MTs during Chlamydia infection." (PMID 28465429, 2017). "Next, we used siRNA to test whether ARF1 and ARF4 are also required for Golgi complex positioning during WT Chlamydia infection." (PMID 28465429, 2017).
cyst (1 paper, 2017). A sac-like closed membranous structure that may be empty or contain fluid or amorphous material. "Since the failure to observe cyst formation in our Arf4flox/CagCreER animals was unexpected, we used HoxB7-Cre as a second method to delete Arf4." (PMID 28410364, 2017). "However, the degeneration in the ciliary-related mutations starts with cyst formation in the exocrine ducts, which are not observed in the Arf4-defective pancreas." (PMID 28410364, 2017).
cystic kidney disease (1 paper, 2017). A congenital or acquired kidney disorder characterized by the presence of renal cysts. "Arf4 was predicted to be a cystic kidney disease gene based on polycystin-1 and fibrocystin trafficking defects in vitro." (PMID 28410364, 2017). "Overall, our data indicate that Arf4 is dispensable for maintaining normal kidney structure and its loss does not lead to cystic kidney disease." (PMID 28410364, 2017).
cystic kidneys (1 paper, 2017). "While these approaches yield cystic kidneys when other cilia genes are deleted neither yielded any evidence for cystogenesis when Arf4 was deleted." (PMID 28410364, 2017).
lung adenocarcinoma (1 paper, 2013). A carcinoma that arises from the lung and is characterized by the presence of malignant glandular epithelial cells. "Some of the genes such as PIK3CA, TAF15, VAPB, Appl1, Rab5a, ARF4, and XIAP in Merged-module activate the PI3K-Akt pathway and are overexpressed in a manner similar to that of EGFR in lung adenocarcinoma." (PMID 23874428, 2013).
melanoma (1 paper, 2025). A malignant, usually aggressive tumor composed of atypical, neoplastic melanocytes. "NRAS Q61L melanomas were most enriched for modules 7 (C19orf10, ARF4, KDELR2), 13 (TIMM50, ZBED3-AS1, SERPINF1), and 15 (RAP1GAP, OCA2, PAICS)." (PMID 39796775, 2025). "Notable findings include NRAS Q61L melanomas being enriched for modules involving C19orf10 and ARF4, while BRAF V600E melanomas were enriched for modules involving ALAS1 and MYO1B." (PMID 39796775, 2025).
neuroblastoma (1 paper, 2012). Neuroblastoma (NB) is the most common solid, extracranial childhood tumor. "Arf4 is expressed in the hippocampi of 4.5-month-old mice, as well as in primary neurons and Neuro-2a (N2a) neuroblastoma cells, as determined by western blots." (PMID 23050017, 2012).
ZIKV infections (1 paper, 2021). "The K21E substitution (MR766 to MR/PR(prM)) similarly resulted in the loss of an accessible positively charged residue, although the role of the KDEL receptors and Arf4/5 in ZIKV infections is currently unknown." (PMID 34310650, 2021).
infection (20 papers, 2012 to 2025). The state of being infected such as from the introduction of a foreign agent such as serum, vaccine, antigenic substance or organism. "To interrogate the functional role of these host proteins during the P. berghei liver stage infection, we used two pooled siRNAs to knockdown mRNA expression of Arf1, Arf4, and GBF1 in HuH7 cells infected with luciferase-expressing P. berghei (Pb-Luc)." (PMID 38349168, 2024). "and Arf3-, Arf4-, and Arf5-depleted cells, indicating normal progression of the immediate–early and early phases of infection in these cells." (PMID 34440611, 2021). "One approach to circumvent the embryonic lethality of germline Arf4 knockout, reported in a recent study, was to knockdown Arf4 using a lentiviral shRNA infection at E9.5." (PMID 28410364, 2017). "Based on these findings, we conclude that CT813 specifically interacts with and recruits ARF1 and ARF4 to the inclusion membrane during infection." (PMID 28465429, 2017). "However, both the relative infection rate and PV size significantly decreased at 48 hpi with Arf4 and GBF1 depletion." (PMID 38349168, 2024). "Similarly, ARF4 protein levels remained consistent across different infection durations and AIV doses." (PMID 39652582, 2024). "Arf4 increased by 3–4 fold, whereas Arf5 almost doubled in amount at 4 hpi, and both Arfs remained elevated during the entire early phase of infection." (PMID 34440611, 2021). "Finally, we determined the localization of CT813-recruited ARF1 and ARF4 during infection by using cells transfected with low levels of hemagglutinin (HA)-tagged ARF1 and ARF4." (PMID 28465429, 2017). "Finally, we investigated the contribution of ARF1 and ARF4 to the formation of PTM MT cages during infection." (PMID 28465429, 2017). "Another signaling pathway recently identified that may impact Golgi stress due to pathogen infection involves ADP-ribosylation factor (ARF)-4 and the transcription factor CREB3." (PMID 26594142, 2015). "Since ARNO has been shown to activate Arf3 and Arf6 in vitro, we examined whether any additional Arf GTPases promote invasion by depleting Arf3, Arf4, Arf5, and Arf6 individually by siRNA transfection of HeLa cells 72 hr before infection with WT Salmonella." (PMID 22341462, 2012). "In addition, D39 infection down-regulated expression of the S phase-specific cell cycle thymidine kinase 1 (TK1) gene and the ACTB gene (~4-fold) encoding β-actin and the ADP-ribosylating factor ARF4 gene (~4-fold)." (PMID 26566142, 2015). "As demonstrated for the class I Arfs, Arf4, and Arf5 displayed a low level of endogenous expression and membrane recruitment in the MCMV-infected cells immediately after infection, similar to what was observed in the uninfected cells." (PMID 34440611, 2021). "In conclusion, our study demonstrates a significant role of Arf1, Arf3, Arf4, and Arf6 in the pathogenesis of CMV infection and host cell reorganization during the early phase of infection." (PMID 34440611, 2021). "Recent studies have shown that ARF4 and ARF5 are involved in distinct steps of the infection cycle of RNA viruses, demonstrating different functions for class II ARF proteins." (PMID 30655362, 2019). "Only ARF1 and ARF4 coimmunoprecipitated with CT813 in CT813-FLAG-tagged Chlamydia-infected cells, demonstrating that the interaction occurs during infection and confirming its specificity." (PMID 28465429, 2017). "Cells depleted of ARF4 or CREB3 contain increased levels of ARF1, 3, and 5, and are more resistant to infection with Chlamydia and Shigella." (PMID 26594142, 2015). "We next studied the localization of Arf1, Arf4, and GBF1 during P. berghei liver stage infection." (PMID 38349168, 2024). "Note that Golgi complex morphology in noninfected cells is not affected by ARF1- or ARF4-siRNA treatment, suggesting that the effect observed during infection is not due to a global Golgi complex defect (data not shown)." (PMID 28465429, 2017).
infection (continued). "We found gene depletion of Arf4 and GBF1 had no impact on the relative infection rate at 4 hpi, indicating that parasite invasion was not hindered." (PMID 38349168, 2024). "In contrast, the Golgi complex remained compact in either ARF1 or ARF4 siRNA-treated cells (ARF1 siRNA and ARF4 siRNA), demonstrating that both ARF isoforms are involved in Golgi complex positioning during infection and that their functions are not redundant." (PMID 28465429, 2017).
cancer (9 papers, 2013 to 2025). A tumor composed of atypical neoplastic, often pleomorphic cells that invade other tissues. "Also, ARF4 is reported to be upregulated in Epithelial ovarian cancer as well as in other major cancer tissues." (PMID 32899424, 2020). "As a representative example, we selected ADP-ribosylation factor 4 (ARF4), a small GTPase implicated in epidermal growth-factor signaling, COPI vesicle formation, recycling-endosome integrity, ciliogenesis, and several disease processes, including cancer progression and cholera-toxin activation." (PMID 40894740, 2025). "ARFs family (ARF1, ARF3, ARF4, ARF5, ARF6) are generally highly expressed in Pan-cancer." (PMID 38617932, 2024). "The cancer promoting effects of ARF1, ARF3, ARF4 and ARF6 in individual cancers have been studied, only the role of ARF5 in cancer has not been reported." (PMID 38617932, 2024).
tumor (5 papers, 2017 to 2025). "Here, we focused on ARF4 in view of its association with the anti-apoptotic effects of tumor cells." (PMID 34556124, 2021). "miR-221-3p plays a tumor suppressor role by affecting ARF4 to repress the proliferation and migration of EOC cells." (PMID 34721577, 2021). "In this feasibility study, several proteins were identified that positively correlated to tumor tissue content including IF6, ARF4, MUC18, UBC12, CSPG4, PCNA, PMEL and MAGD2." (PMID 28445515, 2017). "This combination potentially reduces tumor progression by targeting centrin-specific protease 1 (SENP1) and ADP-ribosylation factor 4 (ARF4) and decreasing the production of α-smooth muscle actin and tropomyosin-1 confirmed in both laboratory and animal model studies." (PMID 40625740, 2025).
genetic diseases (1 paper, 2023). "ARF4 regulates ciliary protein trafficking, dysfunction of which is a known cause of human genetic diseases and syndromic disorders known as ciliopathies." (PMID 37752218, 2023).
neurodegenerative disease (1 paper, 2012). A disorder of the central nervous system characterized by gradual and progressive loss of neural tissue and neurologic function. "We next examined Arf4′s role in spine development in the context of a neurodegenerative disease model." (PMID 23050017, 2012).
ARF4 also shares sentences with these, for which no sentence is quoted: esophageal cancer (2 papers); gastric cancer (2); COVID-19 (1); diabetic kidney disease (1); glioma (1); Infertility (1); Insulin resistance (1); nasopharyngeal carcinoma (1); non-small cell lung carcinoma (1); Obesity (1); polycystic kidney disease (1); skin cutaneous melanoma (1).